SMAD3 (SMAD family member 3)
Diseases named in the same sentence as SMAD3 in open-access papers (continued):
Sharing a sentence is not in itself a finding about the gene and the disease.
cancer (continued). "Recent studies have shown that SMAD3 can have a dual role in repressing and promoting cancer by inhibiting cell proliferation and regulating transcriptional output favouring metastasis, respectively." (PMID 35201514, 2021). "As for SMAD3 function in cancer, most studies unanimously shown that SMAD3 promotes cancer progression and metastasis." (PMID 34048444, 2021). "We have developed natural compound formula AANG, which is derived from traditional Chinese medicine (TCM) and effectively inhibited Smad3‐dependent cancer progression in mice via suppressing Smad3 but reactivating Smad7 in the TME." (PMID 34514726, 2021). "Stage 4 is characterized by high progression of cancer, and therefore, only SMAD3, SMAD5, and SMAD9 showed prognostic significance in this stage." (PMID 34138687, 2021). "Dramatic reduction in Smad7 but activation of Smad3 occurs in many inflammatory disease conditions including cancer." (PMID 34514726, 2021). "We successfully optimized our TCM‐derived natural compound formula AANG for the multidrug resistant HCC, which specifically inhibited Smad3 activation but up‐regulated Smad7 expression in both cancer cells and the TME in vitro and in vivo." (PMID 34514726, 2021). "miR-16-5p has been shown to inhibit cell proliferation in different types of cancers by targeting SMAD3 or cell cycle-related genes." (PMID 34887859, 2021). "We found that suppression of TGF‐β signaling by polyI:C promoted cancer cell death, which was attenuated by forced expression of constitutively active Smad3." (PMID 33342034, 2021). "As our expected, the protein expressions of cancer stemness associated regulators, including TGF-β, Oct-4, Nanog, and p-Smad3 activation, were significantly reduced 30~97% by melatonin, HBO, and combined treatments." (PMID 34671196, 2021). "In cancer cells, Nur77 silencing inhibits the phospho-SMAD3 expression and transcriptional activity in response to TGF-β." (PMID 33562500, 2021). "Genome-wide analyses further identified that USP7 is specifically required for the transcriptional activation of SMAD3, which is involved in repressing cancer cell proliferation." (PMID 34580281, 2021). "STRING and Cytoscape analysis presented four genes, PTEN, CREB1, CASP3, and SMAD3 as the key genes involved in cancer development." (PMID 34155232, 2021). "TGF-β/Smad3 pathway can reduce the expression of class II major histocompatibility complex antigens to diminish the surface immunogenicity of cancer cells." (PMID 34299192, 2021). "Another study showed that the cell cycle arrest of MCF7 cancer cells occurs due to the regulatory role of ellagic acid on the transforming growth factor-beta/Smad3 (TGFβ/ Smad3) signaling pathway." (PMID 32952942, 2020). "As R-SMAD proteins, the impacts of SMAD2 and SMAD3 on cancer initiation and progression were widely investigated." (PMID 32746934, 2020). "Paradoxically, the overexpression of miR-142-5p targeting Smad3 has been shown to lead to cancer progression through the suppression of TGF-β-induced growth inhibition in cancer cells." (PMID 33081305, 2020). "Consistent with increased BMP-mediated Smad2/3 signaling during cancer progression, BMP signaling through Smad3 occurs preferentially in transformed cells and facilitates cancer cell invasion." (PMID 33266416, 2020). "In HCC, SMAD3 was reported suppressing carcinogenesis in chemically inducing animal models and sustained SMAD3 activation promoted cancer metastasis." (PMID 32746934, 2020). "The acquisition of malignant features, such as EMT, cancer cell stemness, and drug resistance in cancer cells was closely related to TGFβ-SMAD3 signaling pathway." (PMID 33584277, 2020). "Meaningfully, FOSL2 has been identified as the promoter of EMT on TGF-β/Smad3 signaling pathway in advanced cancers." (PMID 32552766, 2020). "Further, we have also provided supportive data to show that Smad3 dependent expression of TMEPAI/PMEPA1 contributes to the growth of cancer cells and invasion." (PMID 31798766, 2019).
cancer (continued). "Clinical studies have also shown that elevated level of exosomal SMAD3 protein or mRNA in the serum of HCC patients can predict cancer progression and poor prognosis." (PMID 31815633, 2019). "In particular, miR-142-5p targets Smad3 thereby suppressing TGFß-induced growth inhibition in cancer cells." (PMID 31551516, 2019). "In this study, according to the results of enrichment analyses, SMAD3 was enriched in the functions of cell death and apoptotic process and a set of Disease Ontology terms about cancer." (PMID 29633893, 2018). "As far as we know, this is the first study to show that SMAD3 protein and mRNA can be transferred between cancer cells spontaneously, highlighting this signaling in HCC metastasis." (PMID 29991801, 2018). "First, qRT-PCR was employed to detect SMAD3 expression in cancer tissues along with normal tissues and four cell lines, including BEAS-2B, H125, HCC827 and A549 cells." (PMID 30594196, 2018). "Xue and colleagues demonstrated that FoxM1 promoted typical EMT cellular pathway TGF-beta-dependent cancer metastasis via sustained activation of SMAD3/SMAD4." (PMID 29416660, 2018). "We found that miR-1 suppressed cancer cell proliferation by regulation of Smad3-mediated aerobic glycolysis." (PMID 28471448, 2017). "Dysregulated TGF-β signaling and its interaction with micrRNA-21 and 145 expression in cancer, as corroborated by the present study presents TGF-β and its signaling mediators, especially Smad3 as an important target for cancer therapy." (PMID 29156696, 2017). "Together with Smad4, Smad2 and Smad3 function as reprogramming factors to regulate cancer development in various ways." (PMID 28471448, 2017). "In vitro study also confirmed this finding that pharmacological inhibition of Smad3 signalling with a SIS3 was capable of enhancing cancer-killing activities in both bone marrow-derived or splenic NK cells." (PMID 28262747, 2017). "We also revealed that the miR-1/Smad3 axis regulated cancer cell metabolism by targeting HIF-1α or by an HIF-1α-dependent mechanism including a positive loop by which Smad3 interacts with and regulates HIF-1α." (PMID 28471448, 2017). "The supportive role of Smad3-dependent microenvironment in cancer metastasis was further examined in mouse metastatic models by intravenously (i.v.)administering LLC-luc or B16F10-luc cells into the mice." (PMID 28262747, 2017). "The present study indicates that the TGFβ effect on cancer stemness is also primarily mediated through Smad3." (PMID 28054666, 2017). "The inhibitory role of Smad3 on bone marrow-derived NK cell immunity was confirmed in vitro; the cancer-killing activity of NK cells differentiated from Smad3−/− bone marrow cells was significantly higher than the Smad3+/+ control." (PMID 28262747, 2017). "Many genes, such as Bcl-xl, kRAS, COX, iNOS, APC, Smad3, STAT3, Ptgs2, Tnfrsf6, p16, Mlh1, Runx3, Dapk, and β-catenin are mutated in stages of carcinogenesis of the UC-associated cancer." (PMID 28621756, 2017). "A similar pattern of cancer progression was observed in Smad3−/− and Smad3+/+ mice bearing a highly invasive melanoma cancer cell line B16F10." (PMID 28262747, 2017). "The oncogene forkhead box M1 was found to interact with Smad3 and sustain the Smad3/Smad4 complex, promoting cancer metastasis induced by TGF-β." (PMID 29183317, 2017). "Smad3 is downstream of the transforming growth factor β (TGF-β) signaling pathway, and the TGF-β/Smad3 signaling pathway is a potent growth inhibitor for most cancer types." (PMID 26695440, 2016). "We used a tissue array to examine the p-SMAD3 expression levels in 5 normal tissues and 16 cancer-adjacent tissues by immunofluorescence." (PMID 27485764, 2016). "We noticed several cell cycle related genes such as CDK1 (↑), CCND1 (↑) and SMAD3 (↓), that have been widely investigated in various cancers." (PMID 27602771, 2016).
cancer (continued). "Consistently with our data, the overexpression of phosphorylated SMAD3 in pre-CRT cancer tissues, was a marker of poor pathological response to fluoropyrimidines-based neoadjuvant CRT in 86 LARC patients." (PMID 26934318, 2016). "Based on its essential role in TGF-β signaling pathway, SMAD3 is related with tumor growth in cancer development." (PMID 27601936, 2016). "By contrast, in 12 of 16 cancer-adjacent tissues exposed to inflammatory insults, acinar cells showed significant elevation of p-SMAD3 expression." (PMID 27485764, 2016). "Our results reveal a new mechanism in which MUC1 promotes cancer progression by mediating Smad3 signaling." (PMID 25714018, 2015). "Recently, BMP7 has been implicated in regulation of cancer pathogenesis and metastasis, possibly due to its ability to counteract TGF-β-induced, SMAD3-dependent EMT." (PMID 26546412, 2015). "Studies by our group and other research groups have shown that phosphorylated Smad3 at the linker region promotes cancer cell proliferation." (PMID 26057631, 2015). "We previously reported that SMAD family member 3 (Smad3) has an important role in maintaining mouse ESC stability, as depletion of Smad3 results in cancer cell-like properties in ESCs and Smad3−/− ESCs are prone to grow large, malignant teratomas." (PMID 25569105, 2015). "E-cadherin is expressed by most epithelial tissues, and certain proteins expressed in cancer cells are also related to E-cadherin, such as Snail, Smad2, and Smad3." (PMID 26373288, 2015). "We extend these findings by investigating the role of TGF-β signalling in promoting migration and motility by imaging the signalling activity in live, individual MDA-MB-231 cancer cells utilizing a novel Smad3 Td-Tomato reporter adenovirus." (PMID 25744371, 2015). "A few recent studies have reported that Smad2, similar as Smad3 and Smad4, is mutant in cancers, but Smad2 plays differential roles from Smad3 and Samd4 in TGF-β signaling." (PMID 25166914, 2014). "SMAD3 knockout mice develop various cancers and SMAD3 expression is known to be cell cycle regulated by ras." (PMID 25236373, 2014). "We then dichotomized the 103 patients based on the protein expressions of ALDH2, CCNE1 and SMAD3 in cancer tissues." (PMID 25408144, 2014). "We found two major types of complexes that are affected by miRNAs during cancer progression; the first contains SMAD3, SMAD2, SMAD4, SMAD6, FOXO1, HOXC8, and SKIL, which are connected to AKT1, which is in turn a key modulator of TGF-B signaling pathway." (PMID 24391925, 2013). "It is likely that this event contributes to elevated Ptp4a3 gene expression in cancer through SMAD3/4 inactivation." (PMID 23555575, 2013). "Of note, similarly rapid kinetics of cancer development were previously reported in Helicobacter bilis-infected Smad3−/− mice, where approximately two-thirds develop inflammation-associated mucinous colon carcinomas as early as 6 weeks post-infection." (PMID 22848611, 2012). "More specifically, Rac1 aids cancer cells to more efficiently antagonize TGF-β1/Smad3-mediated growth inhibition via its ability to promote Smad2 activation." (PMID 21624123, 2011). "For example, Pai1 is induced by TGF-β in muscle satellite cells and MMP9 is an important Smad3 target in the process of cancer cell invasion." (PMID 21949838, 2011). "RBM47 is repressed by several EMT-related transcription factors, such as snail family transcriptional repressor 1 (SNAIL), snail family transcriptional repressor 2 (SLUG), signal transducer and activator of transcription 3 (STAT3), and SMAD family member 3 (SMAD3) in cancer cells." (PMID 41335176, 2025). "Additionally, upregulation of SMAD2 and SMAD3 expression has been observed in the live cancer cell upon exposure to L. sativum extracts." (PMID 41210686, 2025). "Lastly, it is necessary to further explore whether the SMAD3/ITGA6 signaling pathway has similar biological functions in other types of cancer." (PMID 38493128, 2024).
cancer (continued). "Notably, the induction of the lncRNA TGILR by the canonical TGFbeta/SMAD3 signaling is highly conserved in cancer." (PMID 38806480, 2024). "Similar result was observed in HeLa cells, which suggested that Linc00673-V3 could also influence the protein level of Smad3 in other cancer types." (PMID 38527804, 2024). "Indeed, the potential side‐effects of Smad3 inhibitor on cancer patients due to the impairment of host T cell immunity during systemic Smad3 inhibition, which largely limits its further translation." (PMID 37967345, 2024). "It is worth noting however that a reciprocal relationship may also exist in some cancer cell types, as p-SMAD3 has been shown to bind to the BCL3 promoter, upregulating BCL3 in response to TGF-β." (PMID 38195591, 2024). "Thus silencing Smad3 in NK cells remarkably increases IFN-γ production as well as the cytotoxicity against cancer." (PMID 38878186, 2024). "Significant TFs identified within the enhancer regions include SMAD2:SMAD3, EWS-ERG fusion, TWIST1, and TEAD3, which play important roles in regulation of transcription in transforming growth factors and embryonic development and are associated with cancers." (PMID 36936794, 2023). "Several complementary pieces of evidence from preclinical and translational studies indicated that inhibition of the TGF-β/Smad3 pathway could be a potential cancer treatment." (PMID 37205317, 2023). "More studies have demonstrated the pro-cancer role of SMAD3." (PMID 37685308, 2023). "In a mouse model of RCC, ERβ supported cancer cell proliferation, migration and invasion, and could affect the expression of TGFβ/Smad3 signaling to control cancer cell invasion." (PMID 37190141, 2023). "Changes in the expression of numerous genes (CDKN1A, SMAD3, MLH1 and PIK3IP1) caused by mutations in ARID1A contribute to the development of cancer and have been linked to the PI3K/AKT pathway in cell translocation, which was highly likely to become a therapeutic target for OC." (PMID 37525498, 2023). "STAT3 activation exacerbates TGF-β1-induced EMT through Smad3/Snail signaling in cancers." (PMID 38136312, 2023). "Notably, these transitions were found to be mediated by a Smad3-centric gene network in TAMs, highlighting the potential of macrophage-targeted Smad3 interventions as a promising therapeutic approach in cancer immunotherapy." (PMID 37965573, 2023). "We observed that when SMAD3 was in a hypermethylated state, the cancer cells were prone to EMT." (PMID 35085106, 2022). "To validate whether SMAD3 down-regulation was required for RAB26 silence-mediated anti-cancer effect on NSCLC, we additionally overexpressed SMAD3 in RAB26-silenced A549 cells to observe the changes in malignant processes." (PMID 35291909, 2022). "We used 2 TAT peptides to abrogate SMAD3 methylation and therapeutically inhibit cancer metastasis." (PMID 35085106, 2022). "Whether SMAD3 could target RAB26 in other cancer cells to regulate cancer progression is of worth exploring." (PMID 35291909, 2022). "SMAD3 can also affect the proliferation and metastasis of cancer cells." (PMID 35413833, 2022). "Interestingly, we have recently reported that the TGF-β-Smad3 pathway is involved in regulating galectin-9 expression in human cancer and embryonic cells." (PMID 35223897, 2022). "However, the mechanisms responsible for the selective activation of SMAD2 versus SMAD3 during cancer progression are still poorly understood." (PMID 35681731, 2022). "Subsequently, the role of GluOC in promoting cancer cell migration via SMAD3 was further verified." (PMID 35413833, 2022). "We can also observe that SMAD3 can promote the cancer progression, as demonstrated in this study." (PMID 35291909, 2022). "We demonstrate that the selective activation of SMAD3 signaling in hypoxia occurs in a wide variety of cancers and that SMAD2 and SMAD3 exert dichotomous roles in cell invasion, in which SMAD3 drives the invasive properties of cancer cells in vitro and in vivo." (PMID 35681731, 2022).
cancer (continued). "In accordance with our speculation, the anti-cancer effect of RAB26 silence on NSCLC cells was markedly abolished by SMAD3 overexpression." (PMID 35291909, 2022). "TGF-β could promote the progression of tumorigenesis in BC and facilitate cancer cell migration and invasion through the Smad3 signaling pathway." (PMID 36387210, 2022). "Furthermore, Smad3 regulates the expression of epithelial–mesenchymal–transition (EMT) genes, which is associated with cancer metastasis." (PMID 36387210, 2022). "Inhibition of SMAD3 methylation with synthesized peptides blocks cancer cell metastasis." (PMID 35085106, 2022). "In this study, we have shown that SMAD2 and SMAD3 exert distinct effects on cancer cell invasion." (PMID 35681731, 2022). "We also found mutations in SMAD3, a transcription factor belonging to the TGF‐β signaling pathway that plays a key role in many tumors, and in MCTP1 gene, whose mutations have been recently associated with acquired drug resistance in carcinomas." (PMID 35212153, 2022). "The results of ChIP-PCR showed SMAD3 had a strong H3K27ac signal in eight common malignant tumors, suggesting that the SE–TF regulatory network with SMAD3 as the core may be involved in the occurrence and development of a variety of malignant tumors." (PMID 34722892, 2021). "T These results highlight the important role of the TGF-β2/SMAD3 pathway in cancer progression." (PMID 34635639, 2021). "Its target genes BECN1 would induce autophagy and E4BP4 suppressed by TF SMAD3 could promote cancer progression by reducing NK cell development." (PMID 33802957, 2021). "For example, increased TGF‐β enhances antigen‐induced PD‐1 expression on T cells in a SMAD3‐dependent manner, drives exclusion of cytotoxic T cells, and impairs acquisition of a Th1 effector phenotype in a cancer metastasis model which has a limited response to anti‐PD‐L1 therapy." (PMID 33932112, 2021). "In addition, it inhibits cancer lung metastasis, impeding TGF-β1-induced EMT in cancer cells, and preferentially interfering with the Smad3 promoter activity in EMT." (PMID 35046810, 2021). "Meanwhile, SMAD3 has been well known as a metastasis-inducer in a series of cancer types." (PMID 33758603, 2021). "Inhibition of SMAD3 inhibited cancer growth, invasion and metastasis in lung and melanoma cancer." (PMID 34366863, 2021). "The SE–TF regulatory network with SMAD3 as the core TF may participate in the carcinogenesis of malignant tumors." (PMID 34722892, 2021). "This positive association implies that SMAD3 may contribute to EMT and stemness programmes in these cancers, potentially contributing to their aggressiveness and metastatic potential." (PMID 35201514, 2021). "The indispensable genes are directly associated with cancers, especially EGFR, MAX, MNT, SMAD3." (PMID 33968733, 2021). "TMEPA1 may be a downstream effector of Smad and regulator of PTEN; in Smad3-knockdown TNBC cancer cells, decreased growth, motility, and invasion were reversed by overexpressing TMEPA1." (PMID 33805447, 2021). "Furthermore, a specific inhibitor of Smad3 phosphorylation (SIS3) was applied to verify that LHPP repressed EMT of cancer cells by attenuating TGF-β/Smad signaling." (PMID 34608127, 2021). "This suggests the downregulation of SMAD3 by MS13 treatment may inhibit cancer growth and metastasis in AIPC cells." (PMID 34366863, 2021). "Finally, we obtained 60 CRC TFs, and SMAD3 exhibited a strong H3K27ac signal in eight common malignant tumor samples." (PMID 34722892, 2021). "Meanwhile, SMAD3 expression level indicated highly differentiated cancer." (PMID 34138687, 2021). "Activated Smad3 therefore displays differential behaviour in cancer/embryonic vs healthy cells." (PMID 33295886, 2020).